ICAM1 (intercellular adhesion molecule 1)
Diseases named in the same sentence as ICAM1 in open-access papers (continued):
Sharing a sentence is not in itself a finding about the gene and the disease.
endothelial dysfunction (continued). "Endothelial dysfunction is a critical event in vascular inflammation characterized, in part, by elevated surface expression of adhesion molecules such as intercellular adhesion molecule-1 (ICAM-1)." (PMID 32208424, 2020). "In in vitro cell assays, plasma of participants with high PM2.5 exposure induced endothelial dysfunction as evaluated by eNOS and ICAM-1 expression and tube formation." (PMID 33066786, 2020). "Loss of TM and eNOS causes endothelial dysfunction, which results in suppressed generation of activated protein C (APC) by TM-thrombin complex and in upregulation of intercellular adhesion molecule 1 (ICAM-1)." (PMID 32382091, 2020). "An increased concentration of biochemical markers of endothelial dysfunction, such as inter-cellular adhesion molecule 1 (ICAM-1), vascular cell adhesion protein 1 (VCAM-1) and E-selectin, were observed in hypertensive patients with LVH." (PMID 31447695, 2019). "The progression of WMHs in CSVD has been associated with higher expressions of ICAM1, CRP, and MMP9, thus supporting the role of endothelial dysfunction in CSVD." (PMID 31708793, 2019). "The addition of synthetic peptides to human endothelial cells significantly prevents the expression of genes related to endothelial dysfunction and inflammation (eNOS, ICAM-1, VCAM-1, IL-6) and lowers NF-κB activation (all p < 0.05)." (PMID 31466215, 2019). "Inflammatory biomarkers of endothelial dysfunction, such as C-reactive protein (CRP), interleukin-6 (IL-6), intracellular adhesion molecule-1 (ICAM1), and E-selectin, have been widely studied and associated with CSVD in human and animal models." (PMID 31708793, 2019). "Endothelial dysfunction is marked by the upregulation of cellular adhesion molecules, such as ICAM-1 and VCAM-1, that cooperate with chemokines and mediate the adhesion of mononuclear and neutrophil leucocytes." (PMID 31391047, 2019). "Our data not only suggest that ER stress induces transendothelial migration of leukocytes via upregulation of Icam1, Vcam1 and Ccl2 but it also involves O-glycosylation events suggesting a key role for PTMs in endothelial dysfunction." (PMID 31346222, 2019). "Quantitative PCR (performed from whole blood) evaluated the expression of genes coding for PTP1B (PTPN1) and key elements of ERS (GRP78, ATF6, CHOP) or for endothelial dysfunction-related markers (ICAM1 and ET1)." (PMID 31737637, 2019). "Overexpression of Orai1 potentiates the expression of ICAM-1 and VCAM-1, silencing of TRPC1 attenuates cisplatin-induced ICAM-1 expression and endothelial dysfunction and overexpression of TRPC3 enhances TNFα-induced VCAM-1 expression." (PMID 29772843, 2018). "As endothelial ICAM-1 expression can be modulated by mechanical strain, future work is warranted to investigate the endothelial dysfunction in well-defined mechanical and flow-based atherogenic microenvironment." (PMID 31069288, 2018). "The increased expression of cellular adhesion molecules, such as VCAM-1 and ICAM-1, plays an important role in endothelial dysfunction and is essential to recruiting monocytes from the circulation." (PMID 28153917, 2017). "Overall, results of this meta-analysis suggested that adoption of a MD eating pattern decreased biomarkers associated with systemic inflammation (high sensitivity-CRP) and endothelial dysfunction [intercellular adhesion molecule-1 (ICAM-1)]." (PMID 29259973, 2017). "In the current study, ICAM1 staining, as an index of endothelial dysfunction, was markedly increased with hypoperfusion and restored with cilostazol treatment." (PMID 28655874, 2017). "Escin significantly ameliorated endothelial dysfunction (increased serum E-selectin and ICAM-1 and lung Wet/Dry ratio, decreased serum NO), and oxidative and inflammatory responses (increased serum MDA, MPO, IL-6 and TNF-α) (P < 0.05 or P < 0.01)." (PMID 28112272, 2017).
endothelial dysfunction (continued). "In vivo study, bubble-induced EMPs were intravenously injected to the rats and soluble thrombomodulin, intercellular adhesion molecule 1, and vascullar adhesion molecule 1 were involved in evaluating endothelial dysfunction." (PMID 28114372, 2017). "ET-1, MDA, and ICAM-1 were further proven to be sensitive biomarkers with the capacity to indicate endothelial dysfunction and decompression stress." (PMID 28386238, 2017). "When endothelial dysfunction occurs, the expression of ICAM-1, VCAM-1, and MCP-1 in mRNA is upregulated." (PMID 27190988, 2016). "When endothelial dysfunction occurs, the mRNA and protein expression of ICAM-1, VCAM-1, and MCP-1 increases." (PMID 27190988, 2016). "In individuals with endothelial dysfunction the addition of 30 mL/day of uncooked olive oil providing 10.2 mg of flavonoids significantly reduced the inflammation marker ICAM-1 (Δ: −9 pg/nL, p < 0.001)." (PMID 27649255, 2016). "At early stages of vascular inflammation, VCAM-1 and ICAM-1 are upregulated in ECs to facilitate leukocyte adhesion to activated ECs and eventually promote endothelial dysfunction." (PMID 27861612, 2016). "Lastly, we observed that higher levels of a plasma biomarker of endothelial dysfunction (E-selectin) were strongly associated with T2D even after full adjustment, although another CAM (ICAM-1) was attenuated upon adjustment for metabolic risk factors." (PMID 27013319, 2016). "The permanence of the inflammatory condition in the vasculature can induce endothelial dysfunction and activation with an increase in the expression of chemotactic factors and adhesion molecules such as ICAM-1 and VCAM-1." (PMID 26055507, 2015). "The effects of CIT were linked with the strong upregulation of aortic inflammation (ICAM-1 and VCAM-1) and endothelial dysfunction in the atherosclerotic model." (PMID 25933220, 2015). "MRTF-A/B expression decreased, while ICAM-1 expression (a biomarker of endothelial dysfunction) increased in HAoECs cultured in 0.1× HEC-C1 medium." (PMID 26024305, 2015). "Individuals with diabetes tend to exhibit high levels of adhesion molecule markers of endothelial dysfunction – ICAM-1, VCAM-1 and E-selectin." (PMID 25855488, 2015). "Endothelial dysfunction is also accompanied withan increased expression of cell adhesion molecules, such as intercellular adhesion molecule-1 (ICAM-1), vascular cell adhesion molecule-1 (VCAM-1), and inflammatory cytokine secretion." (PMID 26473356, 2015). "Circulating endothelial dysfunction biomarkers included soluble intercellular adhesion molecule-1 (sICAM-1), vascular cell adhesion molecule-1 (sVCAM-1) and soluble E-selectin (sE-selectin)." (PMID 24465662, 2014). "Efforts to define plasma biomarkers for endothelial dysfunction have largely focused on soluble intercellular adhesion molecules (CAMs), including intercellular adhesion molecule 1 (ICAM-1), vascular cell adhesion molecule (VCAM-1), E-selectin and others." (PMID 24968272, 2014). "Certain markers of endothelial dysfunction (ICAM-1 and VCAM-1), inflammation (C-reactive protein) and thrombotic activity (PAI-1) are also reported here for the first time." (PMID 25115868, 2014). "Soluble form of VCAM-1, ICAM-1, and E-selectin are present in plasma and reflect cellular inflammatory status and correlate with endothelial dysfunction." (PMID 24883317, 2014). "There were reductions in concentrations of circulating biomarkers of endothelial dysfunction, E-selectin, ICAM-1 and VCAM-1." (PMID 24646518, 2014). "So far, various toxic effects of IS have been reported, such as endothelial dysfunction, induction of oxidative stress, up-regulation of ICAM-1 and MCP-1, induction of TGF-β1 and NF-κB." (PMID 23874392, 2013). "Our previous cell culture study using a static HDMEC model documented a dose dependent up-regulation of pro-atherogenic adhesion molecules (ICAM-1, VCAM-1), which are associated with the endothelial dysfunction." (PMID 23514369, 2013).
endothelial dysfunction (continued). "ICAM-1, an adhesion factor and, in its soluble form, an indicator of endothelial dysfunction, was found to have an increased secretion in cells after cryopreservation." (PMID 23133548, 2012). "Supporting our results, three different in vitro studies have demonstrated that visfatin induced an endothelial dysfunction by increasing inflammatory and adhesion molecules expression such as ICAM1." (PMID 22815813, 2012). "We showed in the present study that endothelial dysfunction, characterized by a downregulation of eNOS and an upregulation of ICAM-1 in blood vessels occurred in RVLM following chronic systemic inflammation." (PMID 22958438, 2012). "ICAM-1 mediates endothelial dysfunction that facilitates BBB leakage, resulting in the transmigration of blood-derived immune cells in the brain and thereby maintaining a persistent inflammation following TBI." (PMID 21733162, 2011). "In proximity of the YKL-40 encoding gene, locus 1q32.2 has been documented to influence the plasma levels of ICAM-1, an adhesion molecule well-documented to participate in endothelial dysfunction and the development of T2D." (PMID 19421404, 2009). "Circulating markers of systemic inflammation and endothelial dysfunction, such as soluble intercellular adhesion molecule-1 (sICAM-1) and soluble vascular adhesion molecule-1 (sVCAM-1) have been shown to predict future CVD." (PMID 17938729, 2007). "The same polymorphism also modulates the association between PM and inflammation and endothelial dysfunction, as adhesion molecules, vascular cell adhesion molecule-1 (VCAM-1) and intercellular adhesion molecule-1 (ICAM-1) were particularly higher in subjects carrying the GSTM1 null gene." (PMID 40427454, 2025). "Additionally, Protein expression of VCAM1 and ICAM1, known markers of endothelial dysfunction, were also significantly increased by Ng-siRNA, indicating brain endothelial cell activation." (PMID 39367201, 2025). "Furthermore, incubation with oleate even reduced VCAM-1 and ICAM-1 expression and NF-κB activation, and OA mitigated the hazardous effects of other endothelial dysfunction triggers." (PMID 41465574, 2025). "This is consistent with the known pathophysiology of hepatic IRI, where oxidative stress and the release of inflammatory mediators such as TNF-α, IL-6, and ICAM-1 lead to systemic endothelial dysfunction and infiltration of neutrophils in remote organs, including the lungs." (PMID 40429525, 2025). "Additionally, increased apoptosis, the expression of intercellular adhesion molecule-1 (ICAM-1), and disrupted NO synthesis can be indicative of endothelial dysfunction." (PMID 41153645, 2025). "Collectively, these biomarkers capture the pathological continuum from nuclear DNA damage (8‐OHdG) and lipid peroxidation (Ox‐LDL) to endothelial dysfunction (ICAM‐1/E‐selectin), providing a comprehensive insight into preclinical vascular pathology in high‐risk populations." (PMID 40739796, 2025). "Finally, P5P reversed the beneficial impact of 1,25-D3 on neurological injury and endothelial dysfunction by modifying the expression of inflammatory and vascular protection factor-associated proteins such as GLP-1R, VEGF-α, e-NOS, ICAM-1, and VCAM-1." (PMID 40224490, 2025). "Notably, ICAM-1, E-selectin, and P-selectin are adhesion molecules that are closely related to endothelial dysfunction by facilitating monocyte and lymphocyte attachment to endothelial cells." (PMID 39980978, 2025). "Soluble ICAM-1 was used as a marker of endothelial dysfunction." (PMID 38578526, 2025). "This immune activation leads to endothelial dysfunction through multiple convergent pathways: direct cytokine‐mediated endothelial activation (increased ICAM‐1, VCAM‐1, E‐selectin expression), anti‐tTG antibody cross‐reactivity with cerebral endothelium, and systemic inflammatory effects." (PMID 40114993, 2025).
endothelial dysfunction (continued). "Cell adhesion molecule-1 (VCAM-1) and intercellular adhesion molecule-1 (ICAM-1) have been used to assess vascular endothelial cell damage and inflammatory response and to detect the level of endothelial dysfunction, which can help to diagnose and monitor the progression of AD at an early stage." (PMID 40507786, 2025). "Concurrently, endothelial dysfunction, a hallmark of CSVD, is counteracted by DHA through enhanced NO bioavailability via AMPK activation, attenuated expression of adhesion molecules (ICAM-1/VCAM-1), and reduced endothelial lipotoxicity from triglyceride-rich lipoproteins." (PMID 40470292, 2025). "The JAK/STAT3 pathway works closely with leukemia inhibitory factor (LIF) to induce inflammation and endothelial dysfunction, characterized by increased levels of intercellular adhesion molecule-1 (ICAM-1) and vascular cell adhesion molecule-1 (VCAM-1), all of which are hallmarks of preeclampsia." (PMID 39596234, 2024). "Moreover, in endothelial cells and umbilical arteries, resveratrol downregulated endothelial dysfunction genes, such as Caspase-3, ICAM-1, and von Willebrand factor (vWF)." (PMID 39596234, 2024). "Thus, further studies detecting endothelial dysfunction markers such as ZO-1, ICAM-1, and VCAM-1 in the aortic roots by immunofluorescence staining are recommended." (PMID 38839811, 2024). "Furthermore, CDDP also upregulates NF-κB/ICAM-1 to affect the production of nitric oxide (NO) and cGMP, which leads to endothelial dysfunction." (PMID 36761198, 2023). "In addition, it alleviated endothelial dysfunction, led to a decrease in serum E-selectin and ICAM-1, and decreased the level of pro-inflammatory cytokines IL-6 and TNF-α in the serum and MPO, as well as the MDA of the oxidative stress marker." (PMID 37371797, 2023). "As GDM is associated with endothelial dysfunction, we also assessed whether GDM might alter the expression of endothelial dysfunction markers ICAM1 and VCAM1." (PMID 37893034, 2023). "In response to SARS-CoV-2 infection, ICAM1 may be upregulated, leading to increased leukocyte-endothelial cell adhesion and subsequent endothelial dysfunction." (PMID 37239234, 2023). "Regarding its effects on adhesion molecules, NAC revealed to inhibit VCAM-1 and ICAM-1 expression in hydrogen peroxide-stimulated HUVEC and visfatin-treated human microvascular endothelial cells (HMEC), underscoring that endothelial dysfunction is associated with oxidative stress." (PMID 37830604, 2023). "Indeed, the role of TMAO in the modulation of factors strictly related to the development of endothelial dysfunction, such as nitric oxide, adhesion molecules (ICAM-1, VCAM-1, and selectins), and IL-6, has been widely accepted." (PMID 36982880, 2023). "In addition, a study has reported that the biomarkers of endothelial dysfunction, such as soluble intercellular adhesion molecule-1 were elevated in the women with PTB." (PMID 37000887, 2023). "The correlation of indoxyl sulfate with ICAM-1 two sides, and represents the implication of this metabolite in the mechanisms of systemic endothelial dysfunction and the targeted damage exerted on renal tubular cells by enhancing ICAM-1 expression at this level." (PMID 37623837, 2023). "This hypothesis is supported by the findings that vitamin E and N-acetyl cysteine not only inhibit endothelial cell NF-kB activation by preeclamptic plasma, but also ICAM-1 expression, leading to endothelial dysfunction." (PMID 38137108, 2023). "On the other hand, overexpression of miR125a resulted in a decline in ICAM-1 and VCAM-1 expression in human brain microvessel endothelial cells, and our result showed that miR125a positively correlated with markers of endothelial dysfunction (i.e. ICAM-1 and VCAM-1)." (PMID 37917636, 2023).
endothelial dysfunction (continued). "Among these markers, C-reactive protein (CRP), monocyte chemoattractant protein-1 (MCP-1), intercellular adhesion molecule-1 (ICAM-1), and vascular cell adhesion protein 1 (VCAM-1) have all been implicated in endothelial dysfunction and the development of vascular disease." (PMID 37570877, 2023). "Here, we examined whether treatment with ET-1 antagonists BQ123/BQ788 or insulin (1 mU/mL and 10 mU/mL doses can reduce markers associated with endothelial dysfunction ET-1, VCAM1 and ICAM1." (PMID 37893034, 2023). "While only ICAM-1 and adiponectin were significantly related to age, the biomarkers were differently related to other biomarkers of pathological processes, such as oxidative stress, fibrosis, inflammation and endothelial dysfunction." (PMID 37443807, 2023). "In addition, LIF can induce inflammation and endothelial dysfunction by increasing the expression of intercellular adhesion molecule-1 (ICAM-1) and vascular cell adhesion molecule-1 (VCAM-1) through the JAK/STAT3 pathway." (PMID 38235138, 2023). "In addition, the level of an endothelial dysfunction marker (intercellular adhesion molecule 1) showed a positive correlation with miR-155-5p, miR-21-5p and let-7g-5p in migraine patients." (PMID 35682695, 2022). "High expression of ICAM1 is a vascular biomarker of endothelial dysfunction." (PMID 35282277, 2022). "Because FOXO1 contributes to endothelial dysfunction and has been shown to directly bind to the ICAM-1 promoter and activate ICAM-1 transcription, it is plausible to speculate that SIRT6 might modulate oxLDL-induced ICAM-1 expression by targeting FOXO1." (PMID 35246513, 2022). "Leptin also induces endothelial dysfunction (ED) by upregulating vascular adhesion molecules such as intercellular adhesion molecule-1 (ICAM-1) and vascular cell adhesion molecule-1 (VCAM-1) through AKT/GSK3β and Wnt/β-catenin signaling pathways, promoting renal inflammation and vascular remodeling." (PMID 36726470, 2022). "Naringin, for example, reduces plaque progression once it decreases non-high-density lipoprotein cholesterol concentrations and biomarkers of endothelial dysfunction and inhibits the expression of ICAM-1 in endothelial cells, preventing immune cell adhesion and infiltration in the vascular wall." (PMID 35237168, 2022). "In some studies, ICAM-1 is also considered a marker for endothelial dysfunction." (PMID 35268306, 2022). "Moreover, anakinra inhibited the expression of ICAM-1 and E-selectin in monocytes and improved endothelial dysfunction by reducing endoplasmic reticulum stress and the infiltration of inflammatory cells." (PMID 35563294, 2022). "Indeed, endothelial dysfunction and an increased expression of ICAM-1 play roles in the initiation of the inflammatory process, which in turn has been reported to affect the renin-angiotensin system and contribute to hypertension." (PMID 34444896, 2021). "There is evidence that the fluctuations in blood glucose levels known as glycemic variability (GV) has correlation with the endothelial dysfunction T2D patients, characterized by increased expression of adhesion (ICAM-1, VCAM-1) and proinflammatory molecules (IL-8, NF-κB)." (PMID 33572702, 2021). "Moreover, when endothelial dysfunction occurs in the IR state, the expression of ICAM-1 and VCAM-1 is promoted; thus monocytes adhere to endothelial cells in circulation." (PMID 33628325, 2021). "In addition, GSTM1 knockdown induced in vitro upregulation of cell adhesion molecules and markers of endothelial dysfunction, ICAM-1 and VCAM-1, which has also been confirmed in the clinical settings using plasma samples from patients with ESRD." (PMID 33574979, 2021). "ICAM-1 promotes the adhesion of leukocytes and vascular endothelial cells, and subsequently leukocyte activation, which may trigger the endothelial dysfunction, inflammatory response, and blood-vessel remodeling." (PMID 33906674, 2021).